Y_RNA (Y RNA )
Gene: Miscellaneous RNA gene on chromosome 12 (96,979,528 to 96,979,629, reverse strand). Ensembl gene ENSG00000202368.
Homologues: Orthologues: chimpanzee Y_RNA (97% identical), macaque Y_RNA (94% identical). Paralogues in human: RNY3 (89% identical), Y_RNA (89% identical), Y_RNA (88% identical), Y_RNA (87% identical), RNY3P1 (86% identical), Y_RNA (86% identical), RNY3P14 (85% identical), Y_RNA (85% identical), RNY3P2 (84% identical), Y_RNA (84% identical), RNY3P11 (83% identical), RNY3P16 (83% identical), and 94 more.